CRIP1 (cysteine rich protein 1)
Diseases named in the same sentence as CRIP1 in open-access papers (continued):
Sharing a sentence is not in itself a finding about the gene and the disease.
serous ovarian cancer (1 paper, 2021). "Through analysis of the TCGA database, we confirmed that CRIP1 was upregulated in serous ovarian cancer samples and was closely associated with tumour progression." (PMID 34413913, 2021). "However, it is interesting to observe that this result was only seen in the serous ovarian cancer cell line OVCAR3, while CRIP1 expression was relatively unchanged in A2780 cells when compared with normal cells." (PMID 34413913, 2021).
viral infection (1 paper, 2012). "In a transgenic mouse model, CRIP1 over-expression impacted host defense by skewing towards a Th2 phenotype as well as increasing host susceptibility to toxins from pathogens and viral infection." (PMID 22970180, 2012).
Zinc deficiency (1 paper, 2021). A deficiency of the essential metal Zinc; an essential cofactor for many enzymes. "Since zinc deficiency is known to be a cause of OS, we speculate that the downregulation of CRIP1 and CRIP3 is affected by OS-induced pathways that contribute to the reduced availability of zinc in cells." (PMID 34944646, 2021).
cancer (27 papers, 2011 to 2026). A tumor composed of atypical neoplastic, often pleomorphic cells that invade other tissues. "Meanwhile, Kaplan–Meier survival analysis also showed that CRIP1 upregulation positively associated with poor prognosis, which was consistent with the TCGA data in several types of human cancers." (PMID 37409440, 2023). "In addition, its role has been studied in diverse cancer types, suggesting that CRIP1 might be a risk factor for chronic inflammation and systemically affects numerous tissues and organs." (PMID 36329504, 2022). "The exploration of the correlation between CRIP1 expression and the survival and prognosis of patients with cancer will further confirm the feasibility of CRIP1 as an intervention target." (PMID 40118853, 2025). "In cervical cancer, compared with adjacent paracancerous tissues, cancer tissues have higher CRIP1 expression, which promotes the occurrence of EMT." (PMID 40118853, 2025). "Our study found that this CRIP1 is overexpressed in all gynecological tumors in pan-cancer analysis." (PMID 35140819, 2022). "To understand the role of CRIP1 in cancer cell invasion, we carried out another Transwell assay with Matrigel." (PMID 34413913, 2021). "As EMT is a major driver of cancer metastasis, we further verified the relationship between CRIP1 and EMT." (PMID 34413913, 2021). "Up to this stage, the correlation between CRIP1 expression and cancer-related EMT had been confirmed, but how CRIP1 mediated this process remained unclear." (PMID 34413913, 2021). "CRIP1 has been reported to be overexpressed in many cancer tissues and is considered to be an oncogene in tumor development and progression." (PMID 34294833, 2021). "As CRIP1 is a small biomolecule that is easy to probe as a biomarker for cancer, mechanism exploration in-depth is meaningful for clinical therapy of CRC." (PMID 30850009, 2019). "As a member of CRP subfamily of LIM family proteins, CRIP1 has been brought to the forefront due to its simple molecular structure and its clinical potential as a biomarker for cancer." (PMID 30850009, 2019). "The strongest trans eQTL in this pattern was CRIP1, a known marker of cellular proliferation in cancer." (PMID 22144904, 2011). "The results revealed increased recruitment of MDSCs in samples expressing CRIP1, suggesting that targeting CRIP1 could be a viable therapeutic approach for cancer." (PMID 40452814, 2025). "Moreover, it has been reported that cysteine-rich protein 1 (CRP-1) is extensively expressed in various cancers, including HCC, and similarly induces EMT in a manner that activates this pathway." (PMID 38634048, 2024). "Firstly, we identified the expression of CRIP1 in various cancers and focused on OC." (PMID 35140819, 2022). "Moreover, in recent decades, the aberrant expression of CRIP1 in several cancers has attracted increasing attention." (PMID 34413913, 2021). "CRIP1 has also been identified as a marker of cellular proliferation in several types of cancer." (PMID 22144904, 2011). "Additionally, analysis of TCGA data also revealed that CRIP1 was upregulated in various types of cancer compared with the normal tissues, which suggested that CRIP1 may be a crucial oncogene." (PMID 37409440, 2023). "This confirms the previous statement that CRIP1 function may differ depending upon cancer type." (PMID 34413913, 2021). "However, its functional role functional role of CRIP1 in cancer biology is poorly understood." (PMID 34262130, 2021). "However, to date, the functional role of CRIP1 in cancer biology is poorly understood." (PMID 34262130, 2021). "Finally, normal D and cancer 3 retained common markers of CAPs, including RGS5, MCAM, and CRIP1, pathways relating to contractility and cytoskeletal rearrangements, and activity of transcription factors associated with muscle contractility, including MYOG." (PMID 40215177, 2025).
cancer (continued). "IHC score showed that CRIP1 was highly expressed in cancer tissues, in contrast to no expression in adjacent normal tissues (P < 0.01)." (PMID 34413913, 2021). "To date, there is no functional characterization of CRIP1, and its precise role in cancer cells and its impact in prognosis are still unclear." (PMID 23570421, 2013).
tumor (21 papers, 2011 to 2026). "Recent studies have highlighted the involvement of STUB1 in various human malignancies, as it regulates the stability and activity of several tumor-associated transcription factors, such as CRIP1, YAP1, HIF-1α, and c-Myc, thereby influencing tumor growth, invasion, metastasis, and angiogenesis." (PMID 40859326, 2025). "Analyzing the correlation between CRIP1 and PD-L1 expression in different tumors, studying the clinical association between CRIP1 and PD-L1, and combining CRIP1-targeted therapy and anti-PD-L1 therapy may provide new ideas for tumor immunotherapy." (PMID 40118853, 2025). "Therefore, we hypothesized that the different tumor properties exhibited by CRIP1 were associated with the activation of different signaling pathways." (PMID 40118853, 2025). "Moreover, further multivariate Cox analysis showed that CRIP1 and tumor residual were independently associated with OS, which may imply that CRIP1 may be an independent prognostic predictor for OC patients." (PMID 35140819, 2022). "Consistently, CRIP1 depletion significantly suppressed tumor growth and reduced tumor burden in docetaxel-treated LNCaP-DTXr xenografts, indicating restored chemosensitivity in vivo." (PMID 41988531, 2026). "The expression of CRIP1 in tumor tissues is higher than that in adjacent tissues, which is related to higher pathological stage, grade, and lymph node metastasis." (PMID 40118853, 2025). "There is evidence that CRIP1 promotes the migration of tumor cells to different organs by activating Wnt/β-catenin signaling pathway." (PMID 40118853, 2025). "CRIP1 was specific to the tumor region, whereas BCAT1 and FXYD3 were confined to the stromal region." (PMID 39135097, 2024). "Prior research on CRIP1 has predominantly focused on tumors, highlighting its tumor type-specific oncogenic or tumor-suppressive characteristics." (PMID 37766321, 2023). "The study highlights CRIP1 regulates the tumor microenvironment to promote lymphangiogenesis and LM in GC." (PMID 37409440, 2023). "Subsequently, we used the ssGSEA algorithm to excavate the correlation between CRIP1 and tumor-infiltrating immune cells." (PMID 35140819, 2022). "It seems that CRIP1 has tumor type specific oncogenic or tumor suppressive properties, and needs further clarification." (PMID 30850009, 2019). "As the infinite proliferation of tumor cells attribute to the chemoresistance for tumor chemotherapy, the effects of CRIP1 on the proliferation and chemosensitivity of CRC cells were investigated." (PMID 30850009, 2019). "Using serial section, we found that Fas is highly expressed in adjacent non-tumor tissues while CRIP1 is overexpressed in CRC tissues under the same vision (R = 0.1905, P < 0.0001)." (PMID 30850009, 2019). "Functional assays, such as CCK8, TUNEL assay and in vivo tumor growth assay, were used to detect the proliferation, apoptosis and response to 5-FU of CRIP1." (PMID 30850009, 2019). "Cysteine-rich intestinal protein 1 (CRIP1) is highly expressed in human intestine and aberrantly expressed in several types of tumor." (PMID 30850009, 2019). "We therefore combined methylation data from patient tumor tissues and cell lines following decitabine treatment to converge on six genes (CRIP1, G0S2, MLH1, OPN3, S100 and TUBB2A) as the classifier." (PMID 25391133, 2014). "Our findings thus indicate CRIP1 to have tumor type specific oncogenic and tumor suppressor properties needing further pathogenetic clarification." (PMID 22202598, 2011). "CRIP1 expression was considered positive when more than 50% of tumor cells were immunoreactive for the respective protein." (PMID 22202598, 2011). "The combination of anti-programmed cell death ligand 1 (PD-L1) treatment and SX-682 increased CD8+ T-cell infiltration and enhanced anti-tumor activity in CRIP1-overexpressing mice, indicating that CRIP1-involved signaling pathways are critical for tumor immune escape and TME formation." (PMID 40118853, 2025).
tumor (continued). "On the contrary, scholars believe that CRIP1 acts as a tumor suppressor gene." (PMID 40118853, 2025). "In most solid tumors, CRIP1 is thought to be highly expressed and promotes tumor progression." (PMID 40118853, 2025). "In fact, CRIP1 was reported to have tumor-specific oncogenic or tumor-suppressive properties." (PMID 35938037, 2022). "While CRIP1 is abundant in the intestine, it is abnormally expressed in certain types of tumor." (PMID 35884586, 2022). "However, related studies are very limited and the role of CRIP1 is controversial in different tumor types." (PMID 30850009, 2019). "Moreover, CRIP1 also dramatically recovered the 5-Fluorouracil (5-FU) induced tumor cell apoptosis in vitro." (PMID 30850009, 2019). "However, studies on CRIP1 are limited and its role on tumor development and progression remains controversial and elusive." (PMID 30850009, 2019). "CRIP1 may have tumor-type-specific oncogenic or tumor-suppressive properties." (PMID 35938037, 2022). "In this study, we clarified that CRIP1 has a low expression in NPC, which can predict tumor occurrence and patient survival." (PMID 37766321, 2023). "CRIP1 overexpression significantly promoted lung colonization by tumor cells, as evidenced by enhanced uptake of 18‐fluorodeoxyglucose (FDG) by GC cell colonies within the lungs, whereas CRIP1 knockdown strongly decreased lung metastasis." (PMID 37409440, 2023). "Increased expression of CRIP1 is remarkably related to multiple factors, including FIGO stage (p < 0.001) and tumor status (p < 0.01)." (PMID 35140819, 2022). "CRIP1 is upregulated in exhausted CD8+ T-cells, and the development of inhibitors against CRIP1 may relieve immunosuppression, improve exhausted CD8+ T-cells, and enhance anti-tumor ability." (PMID 40118853, 2025). "Secretion of VEGFC and CCL5 mediated by CRIP1 and CREB1 could reshape the tumor microenvironment into a suitable “soil” which could favor lymphangiogenesis and LM." (PMID 37409440, 2023). "CRIP1 and CREB1 mediated secretion of VEGFC and CCL5 could then reshape the tumor microenvironment into a suitable “soil” which favor lymphangiogenesis and LM in GC." (PMID 37409440, 2023). "CRIP1 could dramatically recover the 5-Fluorouracil (5-FU) inhibited CRC cell proliferation in vitro and stimulate the tumor formation of CRC in vivo, probably through inhibiting CRC cell apoptosis." (PMID 30850009, 2019). "In addition, CRIP1 can promote proteasome inhibitor resistance through the CRIP1/USP7/PA200 axis, which can inhibit the sensitivity of tumor cells to chemotherapeutic drugs such as fluorouracil and gemcitabine to some extent, thus becoming a potential target for immunotherapy." (PMID 40118853, 2025). "Meanwhile, it should also be noted that the expression of CRIP1 was not statistically correlated with the following clinical characteristics: age, histologic grade, lymphatic invasion, venous invasion, anatomic neoplasm subdivision, and tumor residual." (PMID 35140819, 2022). "Therefore, CRIP1 may inhibit cell death to promote tumor growth, but the specific mechanism remains unclear, and the functional heterogeneity of CRIP1 between cells in different tissues has not been well explained." (PMID 40118853, 2025). "In the comparison of differentially expressed genes (DEGs) between LUAD and normal tissues, three genes (FGFBP2, CRIP1, and PRF1) were mainly expressed in normal tissues but not in tumor-derived cells." (PMID 36483553, 2022).
infection (1 paper, 2025). The state of being infected such as from the introduction of a foreign agent such as serum, vaccine, antigenic substance or organism. "We also observed, in congruence with the previous observations in longitudinal Omicron BA.2 breakthrough-infection cohorts, a down-regulation of CRIP1 in naïve B cells." (PMID 41279719, 2025).
CRIP1 also shares sentences with these, for which no sentence is quoted: cardiac hypertrophy (2 papers); ependymoma (2); acute promyelocytic leukemia (1); Alzheimer disease (1); amyloid (1); asthma (1); atherosclerosis (1); breast tumors (1); coronary artery disease (1); gynecological tumors (1); liver disease (1); Lymphatic Metastasis (1); melanoma (1); mesothelioma (1); osteonecrosis (1); osteoporosis (1); Pan (1); Parkinson disease (1); rheumatoid arthritis (1); Sleep apnea (1).